FTO (FTO alpha-ketoglutarate dependent dioxygenase)
Diseases named in the same sentence as FTO in open-access papers (continued):
Sharing a sentence is not in itself a finding about the gene and the disease.
Obesity (continued). "When investigating the causes of high BMI in adolescents, researchers have reported that monogenic obesity (e.g., MC4R mutations) and common genetic variants (e.g., the FTO gene) exert more pronounced effects during adolescence, possibly due to accelerated energy metabolism during puberty." (PMID 41334401, 2025). "At the same time, some secondary factors also contribute to the occurrence of high BMI such as polycystic ovary syndrome (PCOS), hypothyroidism, or genetic predispositions (e.g., gene variants such as FTO and MC4R, which are significantly associated with obesity risk)." (PMID 41334401, 2025). "The correlation of adiponectin with BMI further implicates FTO in obesity-related complications." (PMID 41423640, 2025). "Additionally, a study on piglets enhances our understanding of the role of the FTO gene in the pathogenesis of obesity-related adiposity." (PMID 41423640, 2025). "Importantly, in leukemia survivors, genetic variants in the FTO and MC4R genes, known for their roles in obesity and appetite regulation, affect weight and metabolic health." (PMID 41228239, 2025). "However, biases related to genetic predispositions must be considered, as genes such as FTO, MC4R, PPARG, and TMEM18 are associated with obesity and metabolic disorders, especially in European populations." (PMID 40827223, 2025). "The inclusion of these covariates was based on their established association with both obesity and breast cancer, ensuring that the results for the FTO polymorphism were not confounded by other factors." (PMID 40630163, 2025). "Newborn infants with FTO gain-of-function SNPs like the rs9939609 risk allele, which is associated with increased FTO mRNA levels, appear to be at increased risk for postnatal aberrations of ASC homeostasis and obesity risk when receiving FF." (PMID 40429638, 2025). "In addition, both m6A and m6Am are targets for FTO demethylation, making both modifications relevant in the obesity context." (PMID 41225618, 2025). "Therefore, further research on the genetic relationship between FTO, obesity, and cancer is particularly important." (PMID 40391584, 2025). "Although most of the studies on the role of FTO gene genotype in obesity and body composition have been conducted on the rs9939609 polymorphism, several studies have shown that polymorphisms located in the intron of an FTO gene are associated with each other as haplotypes." (PMID 38556726, 2024). "However, FTO rs17817449 (GT + TT), TT genotypes, and TGs were considered independent predictors for overweight and obesity in Egyptian DS children." (PMID 39706986, 2024). "Moreover, a positive correlation between FTO SNPs and obesity was observed in children, based on subgroup analysis results in a meta‐analysis of Asian obesity risk." (PMID 38973101, 2024). "While some studies have established a connection, others have not found any association between FTO gene polymorphisms and obesity or overweight." (PMID 39253342, 2024). "Therefore, further multicenter large-scale studies with a larger number of cases would be useful to confirm the FTO rs17817449 role in overweight/obesity development in DS." (PMID 39706986, 2024). "Genes such as FTO (fat mass and obesity-associated gene), LEP (leptin), MC4R (melanocortin 4 receptor), and PPARG (peroxisome proliferator-activated receptor gamma) are well-established contributors to obesity susceptibility." (PMID 39390356, 2024). "Given the relationship between obesity and FTO and metabolic parameters, we also hypothesized that FTO affects metabolic parameters." (PMID 39483856, 2024). "The present study evaluated the association of the genetic variants FTO-rs9939609 and MAO-A 30 bp u-VNTR, along with eating behavior and personality traits with obesity in Mayan children from Mexico." (PMID 39130748, 2024). "FTO has long been studied as a promising molecular target for treating obesity." (PMID 38545841, 2024).
Obesity (continued). "Furthermore, epidemiological studies have indicated a significant increase in the incidence of multiple cancers in individuals with high FTO expression and obesity." (PMID 38365891, 2024). "Genetic deletion of FTO in mice leads to postnatal growth retardation and a significant reduction in adipose tissue by enhancing energy expenditure and systemic sympathetic activation, while ubiquitous overexpression of FTO results in obesity by increasing food intake." (PMID 38706718, 2024). "To date, among three out of twenty-two Arab populations, fourteen interactions have been found between the FTO rs9939609, TCF7L2 rs7903146, MC4R rs17782313, and MTHFR rs1801133 polymorphisms and diet or physical activity on obesity and type 2 diabetes outcomes." (PMID 39125399, 2024). "To data, the molecular mechanism to explain unequivocally the association between FTO and obesity risk is not well established." (PMID 39203789, 2024). "The FTO gene may serve as a potential genetic link between psoriasis and obesity, warranting further research for validation." (PMID 38540130, 2024). "A research group in Singapore found that FTO variants, especially rs9939609, which are common in European populations, were significantly associated with obesity in Chinese and Malays but not in Asian Indians." (PMID 39457458, 2024). "In contrast, however, a meta-analysis conducted in 2014 failed to establish a clear link between protein intake, FTO genetic variants and obesity." (PMID 38281958, 2024). "FTO was initially reported to be closely related to obesity diseases." (PMID 38200441, 2024). "Experimental studies confirmed the link between FTO and obesity also in animal models." (PMID 39744011, 2024). "Notably, the most significant pleiotropic SNP was rs1558902 (PCPASSOC=9.68×10-128) mapped to FTO, a gene known to affect obesity-related phenotypes." (PMID 38529389, 2024). "Lack of FTO protein leads to growth retardation, reduced body weight, white adipose tissue, and increased energy metabolism, while overexpression of FTO leads to obesity in mice." (PMID 38902235, 2024). "However, further research on larger populations and gene–environment interaction studies is necessary to confirm these findings and gain a better understanding of the FTO gene's function in relation to overweight/obesity in children and adolescents." (PMID 38973101, 2024). "Therefore, the aim of this study was to analyze the association of the FTO rs9939609 variant and environmental factors with class III obesity and related variables, including those clinical, anthropometric, and biochemical in nature." (PMID 38610209, 2024). "Several research has also indicated that breastfeeding can impact key genes in the obesity pathway, reducing the expression level of FTO and carnitine palmitoyltransferase IA (CPT1A) genes while increasing the expression level of the PPAR-α gene in 5–6-month-old infants." (PMID 39224127, 2024). "We studied five SNVs in intron 1 of the FTO gene selected from our previous investigations into human obesity and MetS in French, Romanian, and North African populations and extensively studied in human obesity." (PMID 39336743, 2024). "The key genes involved in obesity are FTO, MC4R, LEP, LEPR or PPARG." (PMID 39769194, 2024). "The first model included genetic variants known to be associated with obesity—specifically, ADCY3 rs11676272, CLOCK rs1801260, GPR61 rs41279738, FTO rs1421085, RP11-775H9.2 rs1296328, SLC22A3 rs9364554, and TFAP2B rs734597—and explained 8.3% of the variance in BMI." (PMID 39766774, 2024). "In the realm of Foodomics, our research has elucidated how metabolites derived from Little Millet could aid in obesity treatment by examining their interactions with the FTO protein (4IDZ)." (PMID 39494311, 2024). "Research indicates that specific variations in the FTO gene are significantly linked with obesity, hypertension, and diabetes in white individuals, but not in black individuals." (PMID 39634656, 2024).
Obesity (continued). "In recent years, 52 loci related to obesity have been identified by genome-wide association studies (GWAS) in which the fat mass and obesity-associated gene (FTO), also known as alpha-ketoglutarate-dependent dioxygenase, was one of the first obesity-associated loci described." (PMID 38610209, 2024). "Therefore, the purpose of this study was to analyze the association of the FTO rs9939609: T>A variant and environmental factors with clinical, anthropometric, and biochemical variables in subjects with class III obesity." (PMID 38610209, 2024). "Although some studies confirmed the significant association between FTO and obesity, others did not endorse these results." (PMID 38973101, 2024). "Moreover, FTO inactivation can lead to an increased protection from obesity, and its involvement in adipogenesis was confirmed by studies on animal models, which seem to lose weight when FTO is knocked out and reaches the control group parameters." (PMID 39057082, 2024). "Concordant associations with OP, an increased fracture risk, and a lower BMD at all skeletal sites indicate that the FTO gene is a promising candidate for OP, explaining the complex relationship with obesity and offering new perspectives for the study of the epigenetic regulation of bone metabolism." (PMID 39336743, 2024). "The mechanism responsible for the effect of FTO on obesity is not well known." (PMID 38618529, 2023). "In addition, the same previously genotyped cohort was also investigated for its possible link to obesity, revealing only five allelic variants [FTO and TCF7L2 genes] out of 37 were associated with obesity in the Saudi Arabian population." (PMID 36980809, 2023). "Of note, FTO expression is closely related to weight gain and obesity." (PMID 35731272, 2023). "One of the most well-known obesity-related genes, FTO, was in the gene list." (PMID 37205363, 2023). "Moreover, FTO inhibitors have been demonstrated to improve insulin sensitivity in high fat diets (HFDs) induced obesity." (PMID 37404756, 2023). "Knockout of EC-specific FTO alleviated obesity-induced vascular resistance and increased BP." (PMID 36672629, 2023). "The FTO gene displayed the most robust genetic correlation with polygenic obesity." (PMID 37299548, 2023). "It is well known that inactivation of the FTO gene protects against obesity." (PMID 37781923, 2023). "FTO was originally found to be a critical regulator in obesity and metabolism." (PMID 37781923, 2023). "At the protein level, we observed that active beige adipocytes expressed more UCP1 as compared to white or inactive beige adipocytes regardless the FTO rs1421085 genotypes, however, less UCP1 protein amount was detected in obesity-risk than in risk-free allele carrier active beige adipocytes." (PMID 37416800, 2023). "Earlier studies reported thatPNLIP and FTO genes were found to be potentialtargets for obesity." (PMID 37808366, 2023). "Another gene that is potentially involved in psychiatric disorders and suicide attempts could be the fat mass and obesity-associated gene (FTO), also known as alpha-ketoglutarate-dependent dioxygenase." (PMID 36983683, 2023). "As an obesity-associated protein, early research on the relationship between FTO and cancer mainly emphasized obesity-associated gene polymorphisms, and there was no detailed study of signaling pathways." (PMID 37007161, 2023). "One of the first obesity genes identified is FTO was described in monogenic form." (PMID 37375686, 2023). "For example, macronutrient–gene interactions might affect obesity phenotypes, potentially by regulation of FTO and IRX3 gene expression." (PMID 36979984, 2023). "This cross-sectional study investigates sex differences in the association between FTO single-nucleotide variants and obesity traits among self-identified non-Hispanic Black and non-Hispanic White US adults." (PMID 38064210, 2023).
Obesity (continued). "We aimed to extend this literature using FTO single-nucleotide variants (SNVs) to evaluate sex differences in obesity phenotypes in participants who self-identify as non-Hispanic Black and non-Hispanic White individuals to bridge the research gap." (PMID 38064210, 2023). "According to studies, the FTO gene was related to obesity and certain types of malignancies, including CRC, by altering the impacts of leptin and adiponectin on colorectal carcinogenesis or participating in adipogenesis and tumorigenesis through the mammalian target protein rapamycin (mTOR)." (PMID 37543622, 2023). "Loss of FTO leads to the altered expression of several key components of the brain-derived neurotrophic factor pathway [BDNF, 13], which has been repeatedly linked to polygenic and mono-genetic obesity forms via several molecular mechanisms." (PMID 37223038, 2023). "The FTO is the most well-known gene influencing obesity in children andadults." (PMID 39076398, 2023). "Similar results were reported by other studies: indeed, FTO deficiency has been associated with a reduction in fat and lean mass in mice, while FTO overexpression leads to obesity without affecting skeletal muscle mass." (PMID 37894843, 2023). "On the contrary to risk-free carrier cells, adipocytes with FTO obesity-risk genotype did not consume glutamine irrespective to the applied differentiation protocols." (PMID 37416800, 2023). "Assess the interaction between FTO rs9939609, obesity and dietary fat intake." (PMID 37664850, 2023). "Future particularly molecular studies will validate whether the proposed theories and concepts about the neurodevelopmental role of FTO as a contributor to obesity-promoting behavioral traits hold true in various scenarios." (PMID 37223038, 2023). "The aim of this review is to report new mechanisms affecting FTO expression and to reveal new personalized paths in treating obesity that could be scaled globally." (PMID 37200795, 2023). "Interestingly, there are data showing that FTO inhibitors display also anti-obesity effects in vivo and in vitro." (PMID 35731272, 2023). "In addition, IF intervention decreased the m6A methylation levels and METTL3 expression and increased FTO expression in HFD-induced obesity cardiomyopathy." (PMID 35057432, 2022). "Notably, FTO is the first m6A demethylase that reduces m6A methylation and contributes to inflammation in obesity." (PMID 35712246, 2022). "FTO rs9939609 A allele carriers who consumed ≥1 serving of SSB on a daily basis had a 1.5-fold increased risk of obesity compared to A allele carriers who did not consume any SSBs (p = 0.028)." (PMID 36235854, 2022). "The FTO gene has also been shown to have an impact on the MD benefits to avoid obesity or MetS." (PMID 35327974, 2022). "FTO, as a member of the non-heme Fe(II)- and α-KG-dependent dioxygenase AlkB family, was reported as an obesity-associated gene in previous studies." (PMID 35961973, 2022). "Pinpointing ATG5 and ATG7 as key regulators in FTO-dependent autophagy and adipogenesis further contributes to our understanding of how FTO could be regulating obesity." (PMID 35409166, 2022). "Furthermore, this is, to the best of our knowledge, the first nutrigenetics report regarding FTO and obesity in the Israeli population." (PMID 36235854, 2022). "Our findings demonstrate that the fruit of Solanum has the ability to treat HFD-induced obesity by lowering the FTO gene expression level, as well as curative properties for obesity-related damage to adipose tissue, the hypothalamus, and the liver when taken simultaneously." (PMID 35800074, 2022). "Another possible explanation for obesity’s transgenerational impact might be BPA’s activation of the intronic enhancer of FTO." (PMID 35328389, 2022). "However, 6 BMI index SNPs had positive genetic estimates for both PCOS and pre-eclampsia, including rs1121980 in the adipose-associated gene FTO and rs7498665 in SH2B1, linked to insulin resistance in obesity." (PMID 35104295, 2022).
Obesity (continued). "A growing body of evidence suggests that FTO plays critical roles in both overweight/obesity and cancers via m6A demethylase of target genes, which affecting the stability and/or splicing of their mRNAs, in turn leading to promoting adipogenesis, tumorigenesis and drug resistance of cancer cells." (PMID 36403211, 2022). "Some studies have suggested that the FTO gene mediates the progression of OA through obesity." (PMID 35846376, 2022). "Similar to the results from other plants, the human demethylase FTO (fat mass and obesity-associated protein) also has no homologs in poplar." (PMID 36204058, 2022). "Therefore, this study aimed to analyze associations between FTO (rs9939609), FABP2 (rs1799883), and LEP (rs2167270), LEPR (rs1137101), and MC4R (rs17782313) polymorphisms and obesity-related parameters." (PMID 35627568, 2022). "Overall, these results indicate that (a) individual variation in rCBF within a sample with overweight and obesity can be attributed to a common FTO variant, but (b) a weight loss intervention is equally effective at increasing rCBF, regardless of FTO genotype." (PMID 36072887, 2022). "Interestingly, while the deleterious effect of FTO sequence variation on obesity was buffered by physical activity, a six-month exercise intervention failed to change FTO methylation levels in adipocytes, suggesting alternative mechanisms." (PMID 36551003, 2022). "The role of FTO SNPs in the development of obesity and cancer has been gradually revealed." (PMID 36292657, 2022). "Besides obesity, FTO has an important role in tumorigenesis and pathogenicity of different types of cancer." (PMID 35923209, 2022). "Treatment with orlistat, SMF, SAF, or SMF + SAF for 3 weeks after induction of obesity significantly down-regulated the mRNA levels of the FTO gene in all treatment groups (with the exception of group 7) in a dose-dependent manner when compared with the untreated group 2." (PMID 35800074, 2022). "FTO rs9930506 and MC4R rs17782313 polymorphisms and obesity in children." (PMID 36499740, 2022). "However, further studies investigating the relation between FTO heterozygosity and obesity are needed." (PMID 35409166, 2022). "Its action is also based on the selective inhibition of FTO (fat mass and obesity protein)." (PMID 36232910, 2022). "FTO, which belongs to the non-heme Fe(II)- and α-KG-dependent dioxygenase AlkB family, is well-known as an obesity-associated gene." (PMID 35961973, 2022). "FTO, the first identified m6A demethylase, promotes adipogenesis and obesity." (PMID 35282837, 2022). "This has divided scientists studying FTO in obesity into groups hypothesizing that FTO introns act as cis-regulatory sites for adjacent genes, while other groups hypothesize that FTO introns act as auto-regulators." (PMID 35409166, 2022). "Due to the role of FTO in obesity, drugs targeting FTO have been developed." (PMID 36536469, 2022). "The FTO gene is known to be firmly associated with higher body mass index and obesity risk, while the MC4R gene is the most common causative gene of monogenic obesity." (PMID 35845810, 2022). "Previous studies mostly investigated interactions between FTO variants and alcohol consumption and risk for alcohol dependence but not the risk of obesity." (PMID 36235854, 2022). "Previous studies have indicated that FTO is an essential regulator in the development of obesity-induced metabolic and vascular changes and that adiposity-related risk alleles at FTO may predispose individuals to diabetes and cardiovascular events." (PMID 35250867, 2022). "We hypothesized that individuals carrying the obesity predisposing A allele would exhibit lower resting CBF in the frontal lobe, a region shown to be sensitive to both obesity and genetic variation in FTO, compared to T homozygotes." (PMID 36072887, 2022).